ALB (albumin)
Diseases named in the same sentence as ALB in open-access papers (continued):
Sharing a sentence is not in itself a finding about the gene and the disease.
acute kidney injury (continued). "However, potential adverse effects of albumin use include anaphylactic reactions, prion disease transmission, and acute kidney injury (AKI)." (PMID 35252328, 2022). "• Current diagnostic criteria for acute kidney injury (AKI) are based on changes in serum creatinine, thereby facilitating its early diagnosis, which may prevent progression to the hepatorenal syndrome type of AKI (HRS-AKI) and ensure timely treatment with albumin and vasopressors." (PMID 34131658, 2021). "Albeit limitations, the trial reported reduced risk of AKI by Kidney Disease: Improving Global Outcomes (KDIGO) (RR = 0.533, p = 0.048) and Acute Kidney Injury Network (AKIN) criteria (RR = 0.557, p = 0.031) with albumin administration." (PMID 34419128, 2021). "Also, this study showed statistically significant associations between serum albumin level versus total WBC count (p < 0.0001), acute kidney injury (AKI; p = 0.009), bleeding diathesis (p < 0.0001), and occurrence of pregnancy miscarriage (p < 0.0001)." (PMID 33312698, 2020). "The administration of albumin has proven to be more effective than other fluids in achieving this goal, so that it has become a cornerstone for the prevention of PPCD or renal failure after SBP, and treatment of HRS [1••, 2•, 3•]." (PMID 32837825, 2020). "The samestudy revealed that a low serum albumin level (<2.5g/dL) is an independent riskfactor for postoperative bleeding, prolonged ICU stay, prolonged mechanicalventilation, and renal failure." (PMID 31165612, 2019). "Hospital acquired acute kidney injury (HAKI) and mortality among patients with various admission serum albumin levels." (PMID 29927987, 2018). "Functional-AKI was defined by the Acute Kidney Injury Network serum creatinine definition and alternatively by a ≥50% increase in serum cystatin C. Albuminuria was defined as albumin-creatinine ratio >30 mg/g." (PMID 28372541, 2017). "Old age, prior radiographic TB lesion, high serum albumin, and need for dialysis are predictors of LTBI in patients with renal failure." (PMID 25919813, 2015). "Moreover, a combination of inflammatory state and conditions of decreased albumin levels, as encountered in patients with renal failure on hemodialysis, may by increasing both the absolute and relative abundance of LPC, promote detrimental effects of LPCs including LPC 18:1 on endothelium." (PMID 25419657, 2014). "RBP4 levels were also correlated with markers of renal failure, specifically sCr (r = 0.224, p = 0.005), but they were not correlated with BNP (r = −0.005, p = 0.958) and ALB (r = 0.199, p = 0.057) levels." (PMID 24099047, 2013). "In a systematic review, albumin was found to protect the kidney, whereas the carbohydrate-based artificial colloids hydroxyethyl starch (HES) and dextran were frequently associated with acute kidney injury (AKI)." (PMID 21029460, 2010). "Vitamin E‐coated hemodiafilter rescued the reduction of serum albumin and RedALB in a pig model with acute kidney injury (AKI), but the vitamin E‐non‐coated hemodiafilter did not minimize and significantly decreased those when compared with baseline." (PMID 40108938, 2025). "The adjusted restricted cubic spline curve demonstrated a significant non-linear relationship between lactic dehydrogenase-to-albumin ratio (LAR) and the risk of acute kidney injury (AKI) in patients with intracerebral hemorrhage." (PMID 41487425, 2025). "A six-year-old, intact male German Shepherd, weighing 43 kg, was presented with generalized edema formation and acute kidney injury due to a suspected delayed type III hypersensitivity reaction and vasculitis 2 weeks after the administration of human serum albumin (HSA)." (PMID 41158946, 2025). "Low pre-albumin levels are indicative of impaired hepatic synthetic capabilities and malnutrition, signifying a decline in liver physiological capabilities, while higher levels of serum creatinine coincide with acute kidney injury (AKI), additionally worsening liver failure." (PMID 41220690, 2025).
acute kidney injury (continued). "However, there was large heterogeneity in age, septic shock, acute kidney injury, metabolic acidosis, neoplasm, BUN, CRP, and albumin (I2 > 50%)." (PMID 39103964, 2024). "Perioperative albumin infusion, guided by CRS + HIPEC guidelines, did not elevate the risk of renal failure." (PMID 39664174, 2024). "The estimated glomerular filtration rate and albumin-creatinine ratio were reported to be independent predictors of future acute kidney injury, CVD, CKD, nonfatal cardiovascular accidents, and death." (PMID 39421979, 2024). "In addition, lymphocyte and Ig classes’ recovery to normal-for-age levels lasted longer in cases with high-stage disease, acute kidney injury, high platelet-lymphocyte ratio, %mono, ESR, and low albumin levels at diagnosis." (PMID 38792653, 2024). "For both patients with and without renal failure, age, target organ damage and albumin level < 2.5 g/dL were significant." (PMID 38590318, 2024). "Furthermore, the incidence of renal failure (p = 0.003) and pulmonary infection (p = 0.042) was increased significantly in the high MELD-albumin group." (PMID 35845070, 2022). "Acute kidney failure can be triggered by events such as overdose of diuretics, gastrointestinal bleeding, large-volume paracentesis without albumin replacement, and bacterial infections." (PMID 35237687, 2022). "CPFA is currently used in the treatment of patients suffering from acute kidney injury (AKI) and septic shock, due to its efficacy in the removal of cytokines and inflammatory mediators without significant loss of albumin." (PMID 32710265, 2021). "The findings presented herein showing that oxidized albumin did not appear to play an important role in altering the extent of binding by renal failure cannot be fully explained at this time." (PMID 34822595, 2021). "Inflammation is recognized as increase in concentration of positive acute phase proteins such as CRP (reaching as high as 5-10 mg/dL in renal failure) and decrease in negative acute phase proteins such as albumin and transferrin." (PMID 28487874, 2017). "All the studies noted a transient acute kidney injury, which resolved spontaneously or with conservative management and a non-significant reduction in serum albumin levels." (PMID 30363221, 2017). "Essentially, this means that elevated ex vivo levels of albumin S-cysteinylation are likely to occur faster in patients with renal failure than in patients without elevated plasma cysteine or cystine." (PMID 26181416, 2015). "To date, the use of albumin has been widely accepted for the following three indications: management of HRS, prevention of renal failure after SBP and prevention of renal injury following large volume paracentesis; however, many questions regarding the efficacy and safety of albumin remain." (PMID 26178624, 2015). "Second, the minimum effective albumin dose needed to prevent renal failure in SBP has not been established." (PMID 26178624, 2015). "One month before admission, routine follow-up revealed the onset of NS (4 + proteinuria, 24 h UTP 10.93 g/d, serum albumin 23.2 g/L, LDL-C 8.76 mmol/L) with acute kidney injury (AKI) (serum creatinine 138.2 μmol/L) and radiographic disease progression." (PMID 41244787, 2025). "In our study, postoperative albumin was not a contributing factor to acute kidney injury in elderly patients with hip fractures after surgery, which may be related to differences in the study population, study region, and total sample size." (PMID 40540489, 2025). "However, no previous studies have evaluated the serum albumin redox state in patients with acute kidney injury during hemodialysis therapy." (PMID 40108938, 2025). "The relationship between early human albumin treatment and 28-day mortality was still significant in other subgroups, including age < 75 or age ≥ 75, with or without heart failure, without renal failure, non-glucocorticoid use, SOFA ≤ 10, and mild or moderate hypoxemia." (PMID 37089426, 2023).
acute kidney injury (continued). "All patients had blood calcium corrected for albumin level (total and ionized) assessed, and there were no cases of renal failure that may interfere with the assessment of PTH, calcemic or urinary electrolyte excretion." (PMID 37568342, 2023). "The relationship between albumin corrected anion gap (ACAG) and mortality in acute kidney injury (AKI) patients who received continuous renal replacement therapy (CRRT) has not been investigated in any previous studies." (PMID 36112320, 2022). "Other baseline characteristics of the primary nonresponders included a mean body mass index of 25.9 kg/m2 (range 21.2–34.8); an eGFR (no acute kidney injury) of 87.8 ml/min per 1.73 m2 (range 35–129); proteinuria 10.1 g/d (range 4.9–11.8), and a mean serum albumin 19.1/l (range 14–30)." (PMID 35005317, 2022). "Albumin is the standard of care for some liver-related decompensations, reducing the incidence of renal impairment in spontaneous bacterial peritonitis (SBP) and preventing renal failure after massive paracentesis; it is also used as an add-on therapy for hepatorenal syndrome (HRS)." (PMID 34768404, 2021). "For kidney injury, medical treatment has exclusively consisted of terlipressin in combination with albumin, specifically for patients with HRS, and volume replacement with albumin for patients with acute kidney injury (AKI)." (PMID 34064207, 2021). "Thus, administration of progressively increasing albumin concentrations does not seem to be effective at minimizing acute kidney injury." (PMID 31311539, 2019). "Patients may be in relapses or remission, some patients require treatment with IV albumin infusion and diuretics, patents can be on different and changing doses of medications known to affect BP, and occasionally patients may develop acute kidney injury (AKI) as a complication of NS." (PMID 31380323, 2019). "The hyperphosphatemic group had lower Glasgow Coma Scale, mean arterial blood pressure, hemoglobin level, albumin, and higher TBSA of burns, APACHE II score, ABSI score, Acute kidney injury (AKI), and creatinine." (PMID 29315336, 2018). "Interestingly, [Met(O)]/[Met] for serum albumin (Met-111 and Met-147) and of Igγ1 chain C region (Met-135) were high in type 2 diabetic subjects with normal renal function and in those with renal failure, compared to non-smoking control subjects." (PMID 27929071, 2016). "With regard to HRS–Acute kidney injury (AKI), a multicenter prospective RCT is currently ongoing to evaluate the efficacy of TIPS within 72 h from HRS-AKI diagnosis, compared to the standard of care with terlipressin and albumin (NCT05346393)." (PMID 38592162, 2024). "This study aimed to assess the predictors of acute kidney injury (AKI) during colistin therapy in a cohort of patients with bloodstream infections (BSI) due to colistin-susceptible Gram-negative bacteria, focusing on the role of serum albumin levels." (PMID 30097635, 2018). "The dose-dependent benefits of albumin hold for patients with HRS and non-HRS renal failure." (PMID 26178624, 2015). "However, the relationship between RDW-to-albumin ratio (RAR) and acute kidney injury (AKI) in acute pancreatitis (AP) patients has not been clarified." (PMID 41758789, 2026).
liver cirrhosis (428 papers, 2005 to 2026). "Our findings show that a high MELD score, infection, high Child-Pugh-Turcotte stage, high SCr, high serum bilirubin, and low serum albumin were significantly associated with a high incidence of AKI in liver cirrhosis patients." (PMID 38361702, 2024). "The AASL (age, albumin, sex, and liver cirrhosis)-HCC scoring system, real-world risk score for hepatocellular carcinoma (RWS-HCC), and Chinese University (CU)-HCC score were used for the prediction of HCC risk in CHB patients, taking cirrhosis into account." (PMID 38817899, 2024). "Before PSM, patients with reduced albumin levels showed a higher prevalence of cardiovascular risk factors, liver cirrhosis, nephrotic syndrome, inflammatory bowel disease, infectious and autoimmune diseases, compared to patients with normal albumin levels." (PMID 38323429, 2024). "Toronto HCC risk index (THRI) scoring system, our previous You’an model, the AASL (age, albumin, sex and liver cirrhosis)-HCC scoring system, and real-world risk score for hepatocellular carcinoma (RWS-HCC) were allowed to apply our data." (PMID 38817899, 2024). "Changes in TBIL and albumin often reflect liver function in patients with liver cirrhosis, which is closely associated with a poor prognosis." (PMID 37024814, 2023). "This study showed that older age, higher mean heart rate, lower mean arterial pressure, lower mean temperature, higher SOFA score, higher RDW, and the use of albumin were risk factors for the prognosis of patients with liver cirrhosis complicated with HE." (PMID 37770848, 2023). "Intravenous albumin infusion decreased the risk of renal impairment in patients with liver cirrhosis and SBP." (PMID 38034151, 2023). "Advanced liver cirrhosis has been associated with not only reduced serum albumin but also with the quality of albumin." (PMID 35571233, 2022). "ALB was identified as an independent factor associated with the regression of glucose metabolism disorders in patients with liver cirrhosis." (PMID 35273920, 2022). "High ALB level was associated with the regression of glucose metabolism disorders in patients with liver cirrhosis and severe hepatitis flare." (PMID 35273920, 2022). "High ALB level was associated with regression of glucose metabolism disorders in patients with liver cirrhosis." (PMID 35273920, 2022). "We subsequently evaluated liver-related survival factors in HCV-associated NHL patients, including liver cirrhosis, liver involvement, low levels of albumin (< 3.5 g/dl) and elevated alanine transaminase (ALT)." (PMID 34627251, 2021). "Our results show that HERV-K(HML-2) levels are strongly associated with albumin levels and the presence of liver cirrhosis in HCV-positive patients." (PMID 33807462, 2021). "The decrease in rifampicin CL/F in liver cirrhosis patients is mainly associated with reduction in liver volume and plasma albumin concentration in these patients." (PMID 31694244, 2019). "We found that total RBCs units transfused was associated with age, pre-transplantation serum albumin level, presence of liver cirrhosis, serum BUN, length of operation, and PT." (PMID 30487957, 2018). "Univariate analysis identified three factors to be significantly associated with PSQI-J score 6 or more: presence of liver cirrhosis (LC) (P = 0.0132); our classification of type A; B; C and D (P < 0.0001) and serum albumin level (P = 0.0041)." (PMID 30583494, 2018). "Serum GA values are influenced by several factors associated with albumin turnover independently of glycemia status, such as liver cirrhosis and thyroid dysfunction." (PMID 26765575, 2016). "Decreased serum levels of BCAA and albumin are associated with a high incidence of liver cirrhosis, while supplementation with BCAA has been shown to improve protein malnutrition and increase the serum albumin concentration in cirrhotic patients." (PMID 22312273, 2012).
liver cirrhosis (continued). "The albumin level is clinically important as a predictive factor for patients with liver cirrhosis, because decreased serum albumin levels cause ascites and edema." (PMID 21194423, 2010). "Albumin, as a key indicator of hepatic synthetic function, has been widely acknowledged for its clinical relevance in evaluating the prognosis of patients with liver cirrhosis, as fluctuations in its levels are closely associated with patient outcomes." (PMID 41195174, 2025). "Albumin levels decrease in several conditions, including liver cirrhosis, and so, knowledge of the proportion of zinc bound to albumin may inform alternative or supplementary treatments for those with albumin-depletion-induced zinc deficiency." (PMID 38367035, 2024). "Liver cirrhosis is associated with decreased albumin levels and impaired albumin function." (PMID 38791276, 2024). "Both liver cirrhosis and hepatitis cause a decrease in serum albumin." (PMID 39526239, 2024). "Our findings showed that a high Model for End-Stage Liver Disease (MELD) score, infection, high Child-Pugh-Turcotte stage score, high serum creatinine, high serum bilirubin, and low serum albumin were significantly associated with high incidence of AKI in liver cirrhosis patients." (PMID 38361702, 2024). "Moreover, the levels of albumin and protein C were lower in patients with liver cirrhosis compared to healthy controls, and low levels of albumin and protein C were associated with the increased risk of PVT formation." (PMID 38293307, 2023). "Basili’s study showed that low serum albumin was associated with PVT in patients with liver cirrhosis and found that albumin could inhibit agonist-induced platelet activation, which plays an important role in thrombosis formation." (PMID 36675764, 2023). "Interestingly, different forms of oxidized albumin have been described, which were linked to diseases including diabetes mellitus and liver cirrhosis." (PMID 35740078, 2022). "ALB (OR=1.238, 95% CI: 1.046~1.466) was identified as an independent factor associated with the regression of glucose metabolism disorders in patients with severe hepatitis flare of liver cirrhosis." (PMID 35273920, 2022). "Liver cirrhosis is known to be one of the conditions that predisposes patients to circulatory collapse during anesthesia, likely due to lower circulating plasma volume because of decreased albumin production." (PMID 36572840, 2022). "Therefore, these factors should be taken into consideration when interpreting the GA levels of patients with diseases associated with abnormal albumin homoeostasis (such as nephrotic syndrome, abnormal thyroid function and liver cirrhosis)." (PMID 36251516, 2022). "The comparison of several indicators of the liver function between the two groups revealed that patients in the non-thrombocytopenia group exhibited a lower incidence of underlying liver cirrhosis, lower total bilirubin, higher serum albumin, and shorter prothrombin time (P < 0.05)." (PMID 33573630, 2021). "In addition to the recognized survival factors of NHL, our study also demonstrated that liver cirrhosis and low levels of albumin were inferior prognostic factors of OS for HCV-associated NHL patients." (PMID 34627251, 2021). "Finally, rituximab administration was associated with a favourable OS, while liver cirrhosis and low levels of albumin predicted a poor OS for HCV-positive NHL patients." (PMID 34627251, 2021). "Free flap reconstruction for pharyngeal defect (p < 0.001), preoperative lower serum albumin level (p = 0.04), postoperative lower serum albumin level (p < 0.001), and history of liver cirrhosis (p = 0.037) were all significantly associated with higher probability of high inpatient medical cost." (PMID 32673371, 2020). "Furthermore, tumor stage, albumin, liver cirrhosis, and complement C3 with hybrid glycoform were associated with the mortality rate of HCC." (PMID 31136099, 2019).